RNU6-1097P (RNA, U6 small nuclear 1097, pseudogene)
Gene: Small nuclear RNA gene on chromosome 7 (44,503,773 to 44,503,879, reverse strand). Ensembl gene ENSG00000200456.
Homologues: Orthologues: chimpanzee U6 (100% identical), macaque U6 (96% identical), guinea pig U6 (84% identical), pig U6 (74% identical). Paralogues in human: RNU6-140P (83% identical), RNU6-698P (83% identical), RNU6-1056P (82% identical), RNU6-1310P (82% identical), RNU6-43P (82% identical), RNU6-454P (82% identical), RNU6-46P (82% identical), RNU6-1031P (81% identical), RNU6-1316P (81% identical), RNU6-1329P (81% identical), RNU6-24P (81% identical), RNU6-25P (81% identical), and 1290 more.